RELN (reelin)
Diseases named in the same sentence as RELN in open-access papers (continued):
Sharing a sentence is not in itself a finding about the gene and the disease.
schizophrenia (continued). "A down-regulation of reelin expression occurring in the prefrontal cortex of schizophrenia patients may be associated with a decrease in dendritic spine plasticity, which is probably related to ineffective reelin–integrin interactions." (PMID 38137152, 2023). "Moreover, RELN variants have been proved to contribute to the endophenotypes of schizophrenia and regulate synaptic plasticity and cognition in psychotic subjects." (PMID 35990059, 2022). "Reelin anomalies have long been associated with schizophrenia or behavioral control abnormalities." (PMID 36430976, 2022). "The reelin deficiency model, therefore, provides a mechanism for the altered E-I balance of prefrontal circuits in the pathophysiology of psychiatric disorders, particularly schizophrenia." (PMID 34746116, 2021). "Likewise, defects in neurodevelopment and Reelin expression have been associated with schizophrenia and other neuropsychiatric disorders." (PMID 34708032, 2021). "Indeed, RELN expression is reduced in autism spectrum disorder and schizophrenia and bipolar disorder where it associates with reduced dendritic spine density." (PMID 33964983, 2021). "In summary, the aim of this study was to determine whether risk gene of schizophrenia RELN affects antipsychotic treatment outcomes in the Chinese Han population." (PMID 32082176, 2020). "Our results support our hypothesis that the risk gene of schizophrenia, RELN, can affect antipsychotic treatment outcomes in the Chinese population, suggesting that the susceptibility genes might be potential therapeutic targets." (PMID 32082176, 2020). "Genetic studies have also suggested an association between RELN variants and schizophrenia." (PMID 32764320, 2020). "Population studies have indicated that RELN may contribute to the genetic etiology of schizophrenia, and the known functions of RELN have implicated its involvement in etiology of schizophrenia with regard to a disruption in neurodevelopmental processes." (PMID 32082176, 2020). "Moreover, it has been shown that variants of RELN are closed associated with increased risk of schizophrenia." (PMID 32082176, 2020). "Reelin has been implicated in the development of schizophrenia but the mechanisms involved in this interaction remain unclear." (PMID 32580454, 2020). "In addition, a recent genome-wide association study of schizophrenia revealed that the strongest association was with a marker within RELN, and only in women." (PMID 28118382, 2017). "Studies identified also suggest that treatment-resistance may be differentiated from treatment-responsive schizophrenia by greater repetition of the CCG repeat for the 5’UTR polymorphism on the reelin gene." (PMID 28086761, 2017). "In addition to schizophrenia, reduced expression and REELIN polymorphisms have been reported in some groups of autistic patients." (PMID 27303268, 2016). "Moreover, the pathway is involved in the modulation of synaptic plasticity, learning and memory in the adult brain, and defects in Reelin signalling are associated with neuropsychiatric diseases such as Alzheimer disease, schizophrenia, autism and epilepsy." (PMID 27588423, 2016). "In addition, some RELN gene SNPs have been associated with schizophrenia and bipolar disorder only in women." (PMID 27134686, 2016). "Hippocampal injection(s) of Reelin and its fragments has demonstrated significant improvements in models of Reelin deficiency, Angelman syndrome, and schizophrenia." (PMID 27065802, 2016). "The reduction in Reelin expression occurs most likely through epigenetic mechanisms that affect promoter methylation although evidence for genetic association between schizophrenia and REELIN polymorphisms also exists in patient subpopulations." (PMID 27303268, 2016). "The reduced expression of reelin is associated with schizophrenia and bipolar disorder." (PMID 26035387, 2015). "Several works linked schizophrenia to an imbalance of reelin, Gad67, and Dab-1 expression." (PMID 26526966, 2015).
schizophrenia (continued). "In addition to schizophrenia, reelin deficiencies have been observed in a stress-based animal model of depression and the activity of the nitrinergic system appears to be important for the development of stress and depression symptoms." (PMID 21331324, 2010). "In addition, reelin has been consistently associated with schizophrenia where its expression and immunoreactivity were found to be decreased." (PMID 20421980, 2010). "Deficits in reelin levels and a loss of reelin-positive cells are apparent in brain pathologies such as schizophrenia, depression, and epilepsy and this may be accompanied by alterations in the nitrinergic system." (PMID 21331324, 2010). "Interestingly, Sp1 is involved in the regulation of several genes which have been implicated in schizophrenia such as reelin, GAD67, MAOA/B, NMDA receptor subunits NR1 and NR2A/B, GABA A and DA receptors D1A and D2/3." (PMID 17786189, 2007). "The effect of MEG3 gene variations on the susceptibility to DN could be another instance of genotype-gender interactions in human diseases, just as observations on variants of RELN gene with schizophrenia 46 and polymorphic alleles of ACE gene with hypertension." (PMID 40765563, 2025). "Reductions in Reelin levels and signaling have been found during aging, as well as having been associated with a number of neurological diseases, including ataxias, Alzheimer’s disease (AD), schizophrenia (SZ), and also being partially involved in autism and even traumatic brain injuries (TBI)." (PMID 37891846, 2023). "Moreover, overexpression of the methyl-transferases DNMT1(maintenance methylation) and DNMT3a (de novo methylation) in GABAergic interneurons, which express high levels of reelin, is present in bipolar and schizophrenia and is associated with alterations in mood and synaptic plasticity." (PMID 35203405, 2022). "Both the loss of reelin protein expression, caused by genetic mutation, and prenatal pesticide exposure can alter the shape and connectivity of neurons in several brain regions, providing a possible molecular explanation for neurodevelopmental disorders like autism and schizophrenia." (PMID 27364165, 2016). "Furthermore, such interactions, specifically at the level of NMDA receptors, may be relevant for the disorder as several genetic risk factors for schizophrenia, like Dysbindin, reelin and DISC-1, have been shown to alter NMDA-receptor function in rodents." (PMID 22238649, 2012). "Consistent with this hypothesis, we have recentlyreported a genome-wide association of schizophrenia in an Ashkenazi Jewish (AJ)population that showed a sex-specific association between an intronic singlenucleotide polymorphism (SNP) in the RELN gene and schizophrenia." (PMID 21603580, 2011). "Defects in reelin secretion could play a major role in the development of neuropsychiatric disorders, particularly those associated with deregulation of NMDARs such as schizophrenia." (PMID 19430527, 2009). "Reduced expression and signaling of Reelin has been reported with aging and in a number of neurological diseases, including ataxias, Alzheimer's disease, schizophrenia, autism, and even traumatic brain injuries." (PMID 40837410, 2025). "Human Reelin (RELN) mRNA and protein levels are downregulated in patients with schizophrenia and ASD." (PMID 39931643, 2025). "The present study aims to study the expression profiling of the RELN gene in patients with schizophrenia and the occurrence of metabolic syndrome in these patients." (PMID 39897195, 2025). "A group of researchers from Nanjing Medical University, Wuxi, China performed association studies in the Chinese population to investigate the genetic correlation of RELN with schizophrenia." (PMID 39897195, 2025). "This study, which is the first to investigate the relationship between reelin dysregulation and SC exposure, suggests a potential mechanistic link between SCs and schizophrenia-like symptoms." (PMID 39926699, 2025).
schizophrenia (continued). "In another study, patients with schizophrenia showed greater peripheral blood methylation levels in the RELN gene promoter than healthy controls." (PMID 39897195, 2025). "RT-PCR results revealed a decrease in RELN gene expression in the study group with schizophrenia patients vs. the control group." (PMID 39897195, 2025). "Overall, the expression profile of the RELN gene in schizophrenia has shed light on the gene function in its pathophysiology." (PMID 39897195, 2025). "Studies have reported that downregulation of the RELN gene expression makes a patient prone to psychotic disorders, including schizophrenia and antipsychotic drugs upregulate the gene." (PMID 39897195, 2025). "With this background, we aimed to observe the mRNA expression levels of RELN gene in patients with schizophrenia." (PMID 39897195, 2025). "Patients with clinically diagnosed schizophrenia were studied for RELN gene expression and the RELN protein was quantified using real-time reverse transcriptase-polymerase chain reaction (RT-PCR)." (PMID 39897195, 2025). "Reelin, a protein crucial for brain development, is often found to be reduced in various brain regions of individuals with psychiatric disorders like schizophrenia, bipolar disorder, and major depression." (PMID 39926699, 2025). "They showed that RELN expression was decreased in the blood of untreated patients with schizophrenia." (PMID 39897195, 2025). "The reduction of Reelin in schizophrenia was attributed to a significant increase in 5mC levels at the RELN promoter, with unmethylated Reelin expressed 25-fold higher than methylated Reelin." (PMID 38203806, 2024). "Two neuronal clusters were enriched for genes associated with schizophrenia, the SST neurons and immature neurons that also abundantly expressed RELN (cluster 14)." (PMID 38351133, 2024). "For instance, the levels of Reelin are severely reduced in postmortem brain extracts from patients with chronic psychosis like schizophrenia and autism, behavioral disorders, and epilepsy." (PMID 39062513, 2024). "Genetic studies have shown that there is a relationship between the level of reelin and the occurrence of classical mental diseases, like schizophrenia, bipolar disorder, and autism spectrum disorders." (PMID 39064075, 2024). "Rehabilitation of patients with schizophrenia has been shown to stimulate reelin promoter activity and increase neurocognitive connectivity in the CNS." (PMID 39064075, 2024). "Reelin levels were significantly reduced in schizophrenia patients, with specific gender differences." (PMID 38203806, 2024). "Reelin was found to be altered in various animal models of schizophrenia, suggesting its key role in the pathogenesis of schizophrenia." (PMID 38203806, 2024). "Post-mortem brain samples from individuals diagnosed with major depression, bipolar disorder, and schizophrenia were shown to express a reduced number of Reelin-positive cells in the hippocampus." (PMID 38482060, 2024). "Considered to be crucial in neurogenesis and synaptic plasticity, exploring the role of reelin during neurofeedback therapy provides a molecular perspective on the potential mechanisms occurring during symptom resolution in schizophrenia." (PMID 39064075, 2024). "The aim of this article was to analyze the level of reelin and neurocognitive parameters occurring under the influence of rehabilitation interventions using neurofeedback in patients diagnosed with schizophrenia." (PMID 39064075, 2024). "Genetic studies have confirmed the involvement of reelin system failure in the etiopathogenesis of mental diseases, including schizophrenia." (PMID 39064075, 2024). "Given the reduced levels of reelin observed in the prefrontal cortex of schizophrenia patients, an investigation was conducted to validate reelin’s potential protective role in schizophrenia." (PMID 38137152, 2023).
schizophrenia (continued). "Keywords such as schizophrenia, synaptic plasticity, reelin, neuroplasticity, and mental disorders guided our literature review, with a time frame limited to the last 10 years." (PMID 38137152, 2023). "The relationship between the DNA methylation level of reelin promoters and schizophrenia, derived from the peripheral blood, proved a significantly higher level of methylation compared to controls, and in males compared with females." (PMID 38137152, 2023). "Here we evaluated the validity of a novel gene–gene interaction mouse model of SCZ using mice with mutations in genes associated with schizophrenia, DISC1 and RELN." (PMID 38283751, 2023). "This study aims to explore researchers’ findings on the connection between disorders in the reelin signaling pathway and the development of schizophrenia." (PMID 38137152, 2023). "Taken together, these findings suggest that developmental Reelin signalling abnormalities can promote the development of cognitive deficits attributed to schizophrenia." (PMID 36979424, 2023). "This link is supported by several studies showing that Reelin levels are reduced in patients with schizophrenia, bipolar disorder, and autism spectrum disorder." (PMID 37153634, 2023). "In another study, the expression of reelin mRNA significantly increased in the peripheral blood of schizophrenia patients after 12 weeks of treatment." (PMID 38137152, 2023). "Early studies examining the epigenetic status of candidate genes affected in schizophrenia showed that reelin promoter is hypermethylated in the cortex of subjects diagnosed with schizophrenia." (PMID 36833173, 2023). "Our behavioural data here, and previously, have demonstrated robust MIA-induced cognitive deficits in learning and memory, analogous to those observed following in vivo dysregulation of the Reelin signalling pathway and in schizophrenia patients." (PMID 36979424, 2023). "In post-mortem studies, schizophrenia patients showed a half-reduced concentration of reelin and reelin mRNA in the prefrontal and temporal cortex, as well as in the hippocampus, caudate nucleus, and cerebellum." (PMID 38137152, 2023). "This link is also supported by studies showing that Reelin levels are reduced in patients with schizophrenia and bipolar disorder, and can be altered by psychotropic medication." (PMID 37153634, 2023). "Since reelin is a secreted extracellular matrix protein, measurements of its serum isoforms have been performed for various psychiatric disorders, including schizophrenia." (PMID 38137152, 2023). "Abnormal RELN gene methylation and consequent downregulation has been linked to many neuropsychiatric and neurodevelopmental disorders including ASD, schizophrenia, bipolar disorder, major depression and Alzheimer’s disease." (PMID 36980856, 2023). "In schizophrenia, hypermethylation of the RELN promoter has been identified in several studies, corresponding with reduced RELN expression." (PMID 36979424, 2023). "Although more and more SNPs in RELN are confirmed to be related to schizophrenia recently, their effect on working memory awaits deeper studies." (PMID 35990059, 2022). "Human and animal studies of bipolar, autism spectrum disorder (ASD), and schizophrenia have revealed the presence of hypermethylated RELN promoters, which correlate with a decrease in reelin protein levels." (PMID 35203405, 2022). "Articles focused on psychotic disorders or schizophrenia and their relationship with reelin in rodent models were selected." (PMID 35401125, 2022). "The 37 reviewed articles reported about various schizophrenia models and their reelin alterations, brain morphology, and behavioral defects." (PMID 35401125, 2022). "Reelin is an extracellular matrix glycoprotein reduced in brain regions (the prefrontal cortex and the hippocampus) of patients with schizophrenia." (PMID 35401125, 2022).
schizophrenia (continued). "Our finding indicated that there were hypomethylations of CpG sites in RELN promoter for patients with Schizophrenia when compared to healthy control." (PMID 36216926, 2022). "The missense variation c.9575 C > G (p.T3192S) in RELN was identified by whole-exome sequencing with samples from three affected individuals and one unaffected individual in a Chinese family with schizophrenia." (PMID 35163751, 2022). "RELN mRNA expression levels were elevated in patients with schizophrenia by a 12-week treatment with olanzapine, an antipsychotic, suggesting that alterations in RELN mRNA expression levels are associated with the effects of antipsychotic treatment." (PMID 35163751, 2022). "In both these studies, the expression of the RELN gene was found to be silenced by the high levels of DNAm in patiens with Schizophrenia." (PMID 36216926, 2022). "The essential role of the Reelin gene (RELN) during brain development makes it a prominent candidate in human epigenetic studies of Schizophrenia." (PMID 36216926, 2022). "Heterozygous Reelin-KO mice, a genetic model for schizophrenia, have reduced spine density and abnormal fear memory, which is alleviated by a single in vivo injection of ketamine or a GluN2B antagonist." (PMID 34290083, 2021). "As abnormal Reelin signaling has also been observed in psychiatric disorders like autism, schizophrenia, bipolar disorder, and Alzheimer’s disease, the behavior of mutants for reelin, dab1a and vldlr was analyzed." (PMID 33671313, 2021). "Some studies have reported the hypermethylation of the RELN gene in the post-mortem brain and in peripheral tissue of patients with schizophrenia." (PMID 34831111, 2021). "Using ingenuity pathway analysis, they also determined five main pathways that have been previously identified (Reelin signaling in neurons, VDR/RXR activation, IL-8 signaling, glutathione metabolism, ErbB signaling) to be associated with schizophrenia." (PMID 34502224, 2021). "Reduced reelin mRNA levels have been observed in schizophrenia patients and in post-mortem studies in the hippocampus and cerebellum, basal ganglia and cerebral cortex." (PMID 34070424, 2021). "Many of these target genes, such as RELN, DRD1, VSNL1, and HTR2A, with known function in neural connectivity, have already been associated with the development of schizophrenia." (PMID 32764320, 2020). "Postmortem studies have also revealed decreased Reelin expression in the brains and the cerebrospinal fluid of patients with schizophrenia and ASD." (PMID 32982694, 2020). "Some concordance for methylation status has been observed between blood and brain in relation to schizophrenia candidate genes, including RELN and COMT." (PMID 32764320, 2020). "Both the mRNA and protein levels of RELN have been shown to be markedly reduced in schizophrenia patients." (PMID 32082176, 2020). "Post-mortem studies of individuals with schizophrenia and bipolar disorder with psychosis have shown a 50% down-regulation of reelin within the brain." (PMID 32580454, 2020). "The present results in novel Reln‐del mice modeled after our patient with a novel exonic deletion in RELN are expected to contribute to the development of reelin‐based therapies for schizophrenia." (PMID 32065683, 2020). "Reelin was first found to be involved in neuropsychiatric disorders when a downregulation of reelin expression was observed in the hippocampus of schizophrenia, bipolar, and major depressive disorder patients." (PMID 32982757, 2020). "The reelin pathway is a key contributor to the development of schizophrenia and other neuropsychiatric disorders such as depression and psychosis, and these psychiatric conditions are often comorbid with substance use disorders." (PMID 32647308, 2020).